CXCL8 (C-X-C motif chemokine ligand 8)
Diseases named in the same sentence as CXCL8 in open-access papers (continued):
Sharing a sentence is not in itself a finding about the gene and the disease.
asthma (continued). "This severe asthma cluster was associated with increased expression of CSF3, CXCL2 and CXCL8, genes usually associated with an “IL‐17 signature”,39 although it was evident that expression of these genes was heterogeneous across the cluster." (PMID 32096290, 2020). "MDM galectin-3 secretion was lower in asthma (9.99 (2.67, 15.48) ng/mL) compared with the healthy controls (20.72 (11.28, 27.89) ng/mL; p = 0.044) while IL-6 and CXCL8 levels were similar." (PMID 30606211, 2019). "In this study, galectin-3 secretion by MDMs was lower in participants with asthma compared with healthy participants, while IL-6 and CXCL8 secretion was similar between the groups." (PMID 30606211, 2019). "In patients with moderate to severe asthma, increased expression of CXCL8 has been shown to correlate with raised neutrophil numbers in sputum, which in turn is associated with an increase in the frequency of exacerbations of acute asthma." (PMID 28596972, 2017). "Viral infection can promote elastase, MMP-9, CXCL8 secreted by neutrophils in order to participate in the trajectory of asthma." (PMID 29359169, 2017). "The addition of LL-37 (2 and 10 μg/ml) in eosinophil cultures did not affect the surface expression of adhesion molecules ICAM-1/CD18 or the release of asthma-related inflammatory IL-6, CXCL8 and CCL4." (PMID 28500314, 2017). "We chose to study CXCL8 because it is a key chemoattractant for neutrophils and neutrophilic inflammation is a feature of steroid-resistant asthma, which is difficult to treat." (PMID 25713319, 2015). "Airway smooth muscle (ASM) mass is increased in asthma, and ASM cells from patients with asthma are hyperproliferative and release more IL-6 and CXCL8." (PMID 25697361, 2015). "We believe these changes are not related to fMLF receptor expression since in the same patients with well-controlled asthma; fMLF induced CXCL8 release was approximately half the response of healthy controls but NE release was augmented." (PMID 26663987, 2015). "Studies in humans with asthma and mouse asthma models show that CXCL8 blocking strategies are beneficial." (PMID 25713319, 2015). "Asthma is characterized by airway inflammation and remodeling and CXCL8 is a CXC chemokine that drives steroid-resistant neutrophilic airway inflammation." (PMID 25713319, 2015). "Both IL‐33 and CXCL8/IL‐8 are promising new targets for prevention and therapy of wheezing and asthma." (PMID 26734461, 2015). "Our results show a novel dysregulation of CXCL8 transcriptional regulation in asthma characterized by a promoter complex that is abnormal in ASM cells isolated from asthmatic donors and can be modulated by Brd inhibitors." (PMID 25713319, 2015). "We propose that RV infection in asthma leads to increased release of CXCL8/IL‐8, attracting neutrophils into the airways where they release HNP 1–3, which further enhances airway neutrophilia." (PMID 24673807, 2014). "We propose that RV infection in asthma leads to increased release of CXCL8/IL‐8 thereby attracting neutrophils into the airways where they release HNP 1–3 which further enhances airway neutrophilia." (PMID 24673807, 2014). "In vitro studies using primary BSMCs from donors with asthma have further shown that RV induces greater or equal amounts of IL-6 and CXCL8 in these diseased cells compared to cells from healthy donors." (PMID 23658644, 2013). "In addition, the neutrophils of people with asthma have been shown to have increased migration and NETosis, reduced phagocytosis, and increased proinflammatory cytokines such as CXCL-8 and IL-1β." (PMID 39721985, 2025). "Moreover, epigenetic alterations in genes involved in neutrophil recruitment, such as CXCL8/IL-8 and CXCL1, have been directly linked to the sustained neutrophilic inflammation observed in this asthma subtype." (PMID 40806756, 2025).
asthma (continued). "Thrombin induces the doublecortin like kinase 1/Ras homolog gene family, member A (RhoA) signaling pathway, activating YAP and forming YAP/p65, which enhances IL‐8/chemokine (C–X–C motif) ligand 8 (CXCL8) expression through NF‐κB binding, contributing to asthma development." (PMID 40066231, 2025). "In this study, we investigated whether STK33 mediates thrombin-induced IL-8/CXCL8 release from airway epithelial cells in severe asthma." (PMID 41121245, 2025). "Moreover, in severe exacerbations of COPD or asthma, there are significantly raised sputum CXCL8 concentrations and increased tissue recruitment of neutrophils." (PMID 39598462, 2024). "In addition, Airway Inflammation in Asthma pathway (CXCL8 and RNASE2) was enhanced in the monocyte population." (PMID 37495649, 2023). "According to the prediction results of network pharmacology, IL-6, TNF, CXCL8, IL-10, IL-1β, and IL-4 may be the key targets of Danlong Dingchuan Decoction against asthma." (PMID 35186104, 2022). "Both neutrophils and CXCL8 have been demonstrated in sputum and blood of severe asthma patients." (PMID 34342773, 2022). "Thus, IL-8/CXCL8 has an important crucial pathological role in airway inflammation in severe asthma." (PMID 36369000, 2022). "T2-low asthma is characterized by neutrophilic or paucigranulocytic inflammation and the activation of Th1 and/or Th17 cells, ILC1s, ILC3s and the release of specific cytokines (e.g., CXCL8, IL-17)." (PMID 34342773, 2022). "Both in human and mouse experimental asthma models, IL-17 orchestrates neutrophil recruitment to the lung either directly through CXCL8 production or indirectly through promoting the release of CXCL8, CXCL1, and CXCL5 by structural cells." (PMID 36032162, 2022). "Furthermore, exposure of HBEC3-KT transformed human bronchial epithelial cells (club cells) to the major asthma-associated perennial allergen, HDM extract, induced the production of IL-8 (CXCL8) that was inhibited by BHB in a dose-dependent manner." (PMID 36466740, 2022). "High CXCL8 levels have been reported in treatment-refractory asthma patients, implying that mechanisms driving CXCL8 production may be insensitive to GC therapy." (PMID 35387008, 2021). "HRV infection increases CXCL8 and IL-1β levels in the nasal lavage fluid of patients with asthma." (PMID 32823491, 2020). "Indeed, IL-6 and CXCL8 are known to be increased in HBECs from asthmatics both under baseline conditions and after stimulation, suggesting a regulatory role for miRNAs in the control of IL-6 and CXCL8 expression in asthma." (PMID 33255348, 2020). "Moreover, increased levels of CXCL8 in BALF have been found in patients with severe asthma refractory to glucocorticoids." (PMID 33123138, 2020). "However, elevated concentrations of CXCL8 are found in sputum, bronchoalveolar lavage fluid, and bronchial tissue of patients with respiratory diseases such as severe asthma, occupational asthma, cystic fibrosis, and COPD." (PMID 30828266, 2019). "Interestingly, it has been demonstrated that increased expressions of CXCL8 and eotaxin in ASMCs, as well as an increase of airway smooth muscle area, are seen in patients with severe asthma compared with those with moderate asthma." (PMID 30828266, 2019). "In future, it is very important to investigate whether DEX inhibits OGR1-mediated CXCL8 secretion in ASMCs isolated from patients with steroid-resistant asthma or COPD, because ASMCs of patients with severe asthma seem to be insensitive to corticosteroids." (PMID 30828266, 2019). "Asthma was associated with reductions in RSV‐induced IL‐10 and RV‐induced CXCL8 responses." (PMID 27042305, 2016). "Although our studies focused on ASM CXCL8 production in asthma, the findings may have broader applicability to other diseases driven by neutrophilic inflammation." (PMID 25713319, 2015).
asthma (continued). "In the present work, AT-RvD1 significantly reduced CCL2 and CXCL-8 production in bronchial epithelial cells when compared to cells stimulated with IL-4, demonstrating the potential to reduce both neutrophilic and eosinophilic inflammation in asthma." (PMID 26075216, 2015). "Identifying new mechanisms of CXCL8 modulation may therefore provide targets for treating severe asthma and other inflammatory diseases." (PMID 25713319, 2015). "Dysregulation in CXCL8 induction by RV16 could play a role in the pathogenesis of asthma exacerbations and persistent airway neutrophilia but this requires further investigation." (PMID 26663987, 2015). "It would be of interest in future studies to assess whether increased H3K18Ac is more widespread in ASM cells from asthma subjects (and whole lung tissue incorporating the many cell types involved in asthma pathogenesis) or whether it is specific to CXCL8." (PMID 25713319, 2015). "We previously found that circulating neutrophils from patients with asthma are altered in their response to the viral mimetic, R848 by producing elevated levels of CXCL8, and expression quantitative trait loci mapping in neutrophils has found immune dysfunction trait associated variants." (PMID 26663987, 2015). "Among those, CXCL8 (IL-8), secreted by T lymphocytes, epithelial cells, smooth muscle cells and macrophages might especially be important, as CXCL8 (IL-8) is increased in the airways of patients with asthma." (PMID 17083726, 2006). "In the type 2-low asthma model, Sema3E-deficient mice exhibited increased tissue resistance and elastance, accompanied by elevated levels of neutrophils, dendritic cells, CD4 + T cells, and pro-inflammatory cytokines such as IL-17, TNF, IL-1β, CXCL-8, and MCP-1/CCL2." (PMID 40512736, 2025). "In contrast, in both asthma and COPD, naturally occurring and RV-induced experimental exacerbations are associated with an increase in tissue neutrophils as well as eosinophils, also of interleukin-8 (IL-8,CXCL8) and CC-type chemokine ligand 5 (CCL5) gene expression." (PMID 39598462, 2024). "In this study, the expression of CXCL8 and CXCL1 in ILC3s upon IL-1β stimulation was insensitive to dexamethasone, suggesting that neutrophilic inflammation mediated by IL-1β-ILC3-CXCL8/CXCL1 axis may be involved in the development of steroid-resistant of asthma." (PMID 36949482, 2023). "However, the pathologic role of DCLK1 in asthma and its involvement in thrombin-stimulated IL-8/CXCL8 expression remain unknown." (PMID 36369000, 2022). "Besides, CXCL8 induces lung inflammation in asthma by activating the NF-κB pathway." (PMID 35059042, 2022). "Severe forms of asthma have been associated with mixed granulocytes or neutrophilic inflammation accompanied by T helper 17 (TH17) cells and its associated cytokines [IL-17A, IL-6, granulocyte colony stimulating factor (G-CSF), tumour necrosis factor α (TNF-α), and C-X-C motif ligand 8 (CXCL8)]." (PMID 35387053, 2021). "These lines of evidence suggest that activation of SIRT1 may lead to suppression of neutrophilic inflammation, possibly through suppression of CXCL8 and may be an effective therapeutic strategy, especially for steroid-resistant virus-induced asthma exacerbations." (PMID 32823491, 2020). "Thus, SIRT1 activators, including resveratrol, may be effective in targeting CXCL8-induced neutrophilic airway inflammation in virus-induced and steroid-resistant asthma exacerbations." (PMID 32823491, 2020). "Ex vivo stimulation of airway epithelial cells with NETs can markedly induce endogenous CXCL8/IL-8 production, creating a possible self-amplifying cycle of airway inflammation, consistent with reports of a mucosal epithelial-neutrophil interplay in severe asthma." (PMID 30804927, 2019). "CXCL8 may be a chemoattractant for eosinophils in allergic individuals, but it may also contribute to the neutrophilia seen in the airways in cases of acute asthma exacerbations or severe asthma." (PMID 25883597, 2015).
asthma (continued). "CXCL8 inhibition has until now been speculated to have a role in inflammatory airway diseases, such as chronic obstructive pulmonary disease and severe asthma." (PMID 26633296, 2015). "Strategies to inhibit CXCL8/IL‐8 may be useful in treatment of virus‐induced asthma exacerbations." (PMID 24673807, 2014). "The defect in phagocytosis of bacteria could lead to a persistence of airway bacteria resulting in airway neutrophilia through the release of neutrophilic chemokines such as CXCL8 and possibly to worsening of asthma in terms of severity of symptoms and recurrence of exacerbations." (PMID 24972601, 2014). "Collectively, these findings indicate that thrombin induces IL-8/CXCL8 release through the ERK/STK33/c-Myc pathway, highlighting STK33 as a potential therapeutic target in severe asthma." (PMID 41121245, 2025). "Chemokines such as CXCL8 (IL-8), CCL2 (MCP-1), and CCL5 (RANTES) are significantly upregulated during asthma-related lung inflammation." (PMID 39902079, 2024). "By comparing the enriched signaling pathways in mild asthma and healthy controls, we identified “IL-17 signaling pathway” as the only important signaling pathway in which MUC5AC, MUC5B and CXCL8 showed significant enrichment." (PMID 38351296, 2024). "Interleukin 8 (IL-8), also known as CXCL8, is a chemokine that plays a crucial role in immune responses and inflammation, thus in pathologic conditions such as asthma." (PMID 37570294, 2023). "The top six upregulated DEG genes (IL6, CXCL8, TNF, DUSP2, ADM, and CXCL1) in SR asthma patients compared with SS asthma patients were identified." (PMID 37208441, 2023). "IL-8/CXCL8, thrombin, and DCLK1 expression were observed in the lung tissues of severe asthma patients and ovalbumin (OVA)-induced asthmatic mice model." (PMID 36369000, 2022). "In this study, IL-8/CXCL8, thrombin, and DCLK1 are found to be overexpressed in the lung tissues of severe asthma patient and OVA-challenged asthmatic mice model." (PMID 36369000, 2022). "The clinical and experimental study indicates that high level of IL-8/CXCL8, thrombin, and DCLK1 is related with asthma severity." (PMID 36369000, 2022). "Horses with severe asthma had increased TNF-α, CXCL-8, and IFN-γ concentrations in BALF supernatant." (PMID 36713876, 2022). "Higher levels of CXCL8 in circulation, sputum, and BAL fluid were found in patients with asthma compared to healthy subjects." (PMID 36359917, 2022). "The quantitative analysis indicates a significant increases in the mean intensity fluorescence (MFI) of thrombin by 254.1 ± 41.1%, IL-8/CXCL8 by 245.7 ± 35.0%, and DCLK1 by 212.4 ± 31.0% in severe asthma patients compared to normal." (PMID 36369000, 2022). "Analysis showed that horses with severe asthma had significantly higher TNF-α (p = 0.0005), CXCL-8 (p < 0.0001), and IFN-γ (p = 0.006) compared to healthy horses." (PMID 36713876, 2022). "Circulating PMNs from aspirin-exacerbated asthma patients displayed increased ROS production, CD11b expression and CXCL8 and MMP-9 release compared to aspirin-tolerant asthma patients." (PMID 34342773, 2022). "The merge images show the colocalization of thrombin, IL-8/CXCL8 (MIP-2), and DCLK1 in the lung sections of severe asthma patients or OVA-challenged mice." (PMID 36369000, 2022). "This study demonstrates that IL-8/CXCL8, thrombin, and DCLK1 are overexpressed in the bronchial tissues of severe asthma patients and OVA-induced asthmatic mice." (PMID 36369000, 2022). "IL-8/CXCL8, thrombin, and DCLK1 were overexpressed in the lung tissues of severe asthma patients and ovalbumin (OVA)-induced asthmatic mice model." (PMID 36369000, 2022). "A previous study has found that CXCL8 and IL-1β expression was promoted in both COPD and asthma patients." (PMID 32756014, 2020). "In a preclinical model of asthma, adoptive transfer of allergen-specific TH17 cells to mice induced a chemokine (CXCL8, also known as IL-8)-mediated neutrophil influx into the lung, which was not attenuated by CS." (PMID 29119328, 2017).
asthma (continued). "CXCR2 is a receptor for a number of chemokines such as the GRO family (CXCL1-3) and CXCL8, all of which are elevated in respiratory inflammatory diseases such as COPD, severe asthma, and acute respiratory distress syndrome." (PMID 28596972, 2017). "It is of note that dexamethasone, representing the mainstay treatment of severe asthma, inhibited not only dsRNA-induced BSMC generation of proinflammatory cytokines (TNF-α and CXCL8) but also IFN-β and IFN-λ1 in this study." (PMID 23658644, 2013). "We monitored production of interleukin-6 (IL-6) and interleukin-8 (IL-8) (alias CXCL8), two pro-inflammatory cytokines produced by airway cells that are relevant in asthma pathogenesis." (PMID 23369242, 2013). "The levels of IL-8 (CXCL8), a chemokine, and myeloperoxidase in nasal aspirates increase in children during RV infection-induced asthma exacerbation." (PMID 22966430, 2012). "In human subjects in vivo, elevated tracheal IL-8/CXCL8 levels and neutrophil accumulation are found in airways of patients with asthma, COPD, and viral infection." (PMID 15921526, 2005). "Concurrently, Sema3E KO mice that were subjected to the type-2 low asthma model demonstrated an elevated presence of pulmonary neutrophils, dendritic cells, CD4 T cells, as well as increased levels of IL-17, TNF, IL-1β, CXCL-8, and MCP-1/CCL2 in comparison to their WT counterparts." (PMID 40512736, 2025). "E-cigarette aerosol also triggers the release of IL-8/CXCL8 and MMP-9 and increases neutrophil elastase activity, potentially facilitating neutrophil migration to inflammation sites and exacerbating symptoms in asthma and COPD patients." (PMID 38806787, 2024). "OS biomarkers MDA, FRAP, protein carbonyls, and peroxynitrite, and inflammation biomarkers ILC2/3, MMP-12, CXCL8, neutrophil elastase, AZU-1, and PPBP were found to associate with asthma in smokers, but not in nonsmokers." (PMID 37367073, 2023). "In our study, we found ILC3s produced neutrophil chemoattractants including CXCL8, CXCL1, TNF-α and GM-CSF after IL-1β stimulation, suggesting ILC3s may mediate airway neutrophilia in asthma by release of neutrophil chemoattractants." (PMID 36949482, 2023). "As IL-8/CXCL8 is a potent chemoattractant of neutrophils, its increase will be followed by elevated recruitment of neutrophils to the inflamed area, exacerbating the inflammatory response that leads to severe asthma." (PMID 36369000, 2022). "To confirm whether thrombin, IL-8/CXCL8 (MIP-2), and DCLK1 are highly expressed in lung tissues of asthma patients and OVA-induced mice, we performed triple staining immunofluorescence." (PMID 36369000, 2022). "DCLK1 might be essential in thrombin-stimulated IL-8/CXCL8 expression in asthmatic lungs and indicates a potential therapeutic strategy for severe asthma treatment." (PMID 36369000, 2022). "Similarly, LL-37-exposed cocultures of eosinophils and BEAS-2B cells displayed increased IL-6, IL-8/CXCL-8, and CCL4, while murine LL-37 homolog cRAMP increased bronchial hyperresponsiveness in ovalbumin-induced murine asthma." (PMID 34248677, 2021). "In the majority of asthma patients, primary bronchial epithelial cells were hyperresponsive to IL-17A and proinflammatory stimuli such as TNF-α, reflected by an enhanced production of inflammatory mediators such as CXCL-8, and corticosteroid insensitivity." (PMID 34221070, 2021). "ASMCs from patients with asthma are in a hyperproliferative phase, overexpress the chemokines chemokine (C–C motif) ligand (CCL) 11 (CCL11) and CXCL8, and particularly in patients with severe asthma, there is a reduced effect of corticosteroids in inhibiting TNFα-induced release of CCL11 and CXCL8." (PMID 28842514, 2017). "Interestingly, both p38α MAPK and IKK-2 activities are elevated in severe asthma, as are a number of H3-Pser10-regulated genes including IL-6, CCL-2 and CXCL-8." (PMID 25905622, 2015).